SMAD2 (SMAD family member 2)
Diseases named in the same sentence as SMAD2 in open-access papers (continued):
Sharing a sentence is not in itself a finding about the gene and the disease.
tumor (continued). "LY2109761 (LY) is a novel selective TGF-β receptor type I/II inhibitor that completely inhibits TGF-β-induced SMAD2 phosphorylation and exhibits antitumor effects in various tumor models, such as glioblastoma, oral squamous cell carcinoma and prostate cancer." (PMID 31631064, 2019). "Immunoreactivity to Smad2 was found in the majority of tumor cells in 40.5% (60/148) low grade, and in only 26.6% (68/256) high-grade neoplasms." (PMID 31238579, 2019). "As with the genes involved in the JAK/STAT3 pathway, 10 mg/kg ajoene extract significantly suppressed the expression of Smad2, Smad3, and Smad4 compared with the tumor control group (Smad2, p = 0.012; Smad3, p = 0.049; Smad4, p < 0.001)." (PMID 31717643, 2019). "As a result, YFTL significantly inhibited the phosphorylation of Akt, Erk1/2 and Smad2, and decreased the expression of TGFβ in Lewis tumor tissues." (PMID 30781674, 2019). "Smad2 is a receptor-regulated Smad (R-Smad), a functional class involved in ligand specific, TGF-β-cell-signaling pathways and implicated to function as tumor suppressors." (PMID 31323058, 2019). "Such downregulation of NRP1 in oncogenically KRAS-transformed cells promotes tumor growth by reducing SMAD2 phosphorylation." (PMID 30717262, 2019). "Eighty–one tumor (20%) showed uniform expression of Smad2 and Smad4, while 172 (42.57%) tumors were scored as simultaneously negative/low for the expression of both markers." (PMID 31238579, 2019). "Reduced expression of NRP1 in KRAS-transformed cells results in reduced SMAD2 phosphorylation and increased tumor growth." (PMID 30717262, 2019). "We also found increased levels of phosphorylated Smad2 in the tumor stroma of p38αΔFSP1 mice, consistent with a local upregulation of TGF-β signaling in stromal cells." (PMID 31296856, 2019). "Activated TGF-βRI phosphorylates cytoplasmic SMAD2 and SMAD3 (SMAD2/3) transcription factors, allowing them to be translocated into the nucleus and participate in tumor development." (PMID 31681406, 2019). "Consistent with high levels of TGF-β1, CD133+ tumor cells also expressed higher levels of p-Smad2 than CD133− tumor cells (p = 0.008)." (PMID 29510695, 2018). "Lesional cSCC tissue had significantly reduced activated SMAD2/3 compared to perilesional tissue, consistent with a tumour suppressor role for SMAD2/3 activators in cSCC." (PMID 29581863, 2018). "There are some parallels between tumor progression and early stages of endoderm differentiation, where LINC00261/DEANR1 acts in cis by recruiting the EMT-associated transcription factors SMAD2/3 to the FOXA2 promoter." (PMID 30597925, 2018). "The results revealed that the expression levels of p-Smad2, p-Smad3 and p-c-Myc in the PIM1-deficient tumour edge tissues were significantly lower than those in the control tumour edge tissues." (PMID 29472550, 2018). "Here, high levels of ICN1 seem to cooperate with the TGF-β pathway in the tumor milieu, favoring Smad2/3 phosphorylation, and finally promoting EMT and the survival of tumor-initiating cells." (PMID 30154786, 2018). "Treatment of 4T1-pSMAD-luc tumor cells with M7824 either prior to or after the addition of TGFβ1 reduced TGFβ1-dependent phosphorylation of SMAD2, as indicated by decreased SMAD2 promoter-dependent luciferase activity." (PMID 29721396, 2018). "In KRASmt cells, NRP1 knockdown results in decreased SMAD2 phosphorylation and enhanced tumor growth." (PMID 29018205, 2017). "On the other hand, it can repress another transcription factor, Krüppel-like factor 5 (KLF5), the presence of which can promote SMAD2/3 pathway leading to tumor progression." (PMID 29254283, 2017).
tumor (continued). "IHC of p-Smad2 protein on full-face sections taken from the edges of tumours adjacent to peritoneum lining manifested high expression of p-Smad2 protein." (PMID 29069715, 2017). "Linker phosphorylated Smad2/3 promotes oncogenesis, while C-terminal phosphorylation of Smad3 tend to produce tumor suppression." (PMID 29156696, 2017). "NRP1 knockdown enhanced cell viability and tumor growth and resulted in decreased SMAD2 phosphorylation." (PMID 29018205, 2017). "In mechanism, FOXP3 exerted its tumor inhibition effects probably via the regulation of TGF-β/Smad2/3 pathway." (PMID 28903735, 2017). "All these studies provided us novel ideas in searching for further understandings of tumor inhibition via FOXP3/TGF-β/Smad2/3 pathway." (PMID 28903735, 2017). "Our findings suggest that FOXP3 suppresses tumor progression in HCC via TGF-β/Smad2/3 signaling pathway, highlighting the role of FOXP3 as a prognostic factor and novel target for an optimal therapy against this fatal malignancy." (PMID 28903735, 2017). "Some cancer cells escape the tumour suppressor effects of TGF-beta by down-regulation/mutation of the type 1 and 2 receptors, Smad2 and Smad4." (PMID 29267390, 2017). "The key players of the TGF-β signaling pathway are previous biomarkers such as TGFβR2, Smad2, and Smad4 by tumor biopsy or genetic analysis." (PMID 27916872, 2016). "In support of this model, fibroblasts associated with 4T1 tumours show a significantly increased TGFβ pathway activation compared with 4T07 tumour fibroblasts as monitored by higher phospho-Smad2 levels within the fibroblast nuclei." (PMID 26777421, 2016). "Inhibition of these pathways in vivo in an LL/2 tumor mouse model increased survival, inhibited tumor growth, and decreased angiogenesis associated with decreased RPS6 and SMAD2 phosphorylation." (PMID 27618721, 2016). "For example, SB-431542 was shown to suppress tumor progression by inhibiting the transcriptional activity of p-Smad2/3." (PMID 26769851, 2016). "In Tgfbr2 conditional knockout mice, we observed downregulation of p-Smad2 in tumor cells, which correlated with increase of tumor cell apoptosis and increase of proliferation activity." (PMID 27378170, 2016). "Immunohistochemistry was used to assess the levels of the target integrins of cilengitide, αvβ3 and αvβ5 integrins, of αvβ8 and of their putative target, phosphorylation of SMAD2, in tumor tissues from CENTRIC (n=274) and CORE (n=224)." (PMID 26918452, 2016). "The conversion from an inhibiting to a tumor growth-promoting role has been described for the tumor suppressors Smad2, 3 and 4, which also function as transcriptional repressors." (PMID 26430725, 2015). "Work from the Schiemann laboratory has characterized novel mechanisms by which TGFβ converts from being a Smad2/3-dependent tumor suppressor to a Smad2/3-independent tumor promoter." (PMID 26267863, 2015). "Remarkably, 3D1 also blocks in vitro the interaction of Nodal with Cripto-1, a feature of particular relevance in the context of tumor development mechanisms involving the activation of the Smad2/3 axis." (PMID 26370966, 2015). "Inhibition of TGF-β disrupted activation of Smad2, which has been shown to control metastasis, tumor growth, and the invasion of cancer cells." (PMID 26252213, 2015). "We further reveal that the inhibition of tumor invasion was directly due to the suppression of Smad2 by utilizing siRNA against Smad2." (PMID 25980495, 2015). "Conditional medium of SMAD2 knockdown fibroblast induces proliferation and in vivo deletion of SMAD2 in tumor cells generates a more aggressive phenotype compared to controls." (PMID 26146544, 2015). "Primarily, the SMAD2/3 signaling pathway inhibits proliferation of normal epithelial cells and, hence, is considered to have a tumor-suppressor function." (PMID 28721365, 2015).
tumor (continued). "To confirm the effect of the TβRI inhibitor, we evaluated the phosphorylation of Smad2 and Smad4, which are downstream targets of the receptor, by immunohistochemistry in tumor samples from allergic mice and allergic mice treated with the inhibitor." (PMID 26076663, 2015). "Smad2 is one of the key downstream proteins in the TGF-β signaling pathway to regulate tumor invasion." (PMID 25980495, 2015). "We also observed thatTGFB2, TGFBR1 and SMAD2 genes had greater expressionin tumours with low MEG3 expression, further supporting our invitro cell culture results that MEG3 negatively regulates theTGF-β pathway genes." (PMID 26205790, 2015). "Recent studies showed that Smad2 has a tumor suppressive effect on both tumor growth and malignant conversion, thus making it a promising candidate for cancer therapy." (PMID 25170969, 2014). "Our results suggest that malignant conversion requires a significantly lower level of Smad2 than tumor formation." (PMID 25170969, 2014). "Recently, a few studies have demonstrated that Smad2 expression level in cancer cells is correlated with tumor development and prognosis." (PMID 25373709, 2014). "TGF-β1 mRNA levels were higher in tumor than in peritumor, which positively correlated with Smad2 and Smad7." (PMID 23342108, 2013). "Concerning Tregs, one of the major suppressors of anti-tumour immune surveillance, Smad4-independent development of Tregs in our model and Smad2/3-independent development of nTregs in vivo indicate that Treg development is Smad-independent." (PMID 24127404, 2013). "SB-431542, a small molecular inhibitor of TβIR, had been shown to inhibit TGF-β-induced EMT by regulating the phosphorylation of Smad2/3 in tumor cells, which is consistent with our results." (PMID 23300530, 2012). "Taken together, these results indicate that tumor exosomes specifically activate Smad2/3 and p38 in hucMSCs." (PMID 23285052, 2012). "Real time PCR was used to measure mRNA expression of Smad2 and Smad3 in cancer and surrounding non-tumor tissue." (PMID 22539990, 2012). "The increased phosphorylation of Smad2/3 and p38 following tumor exosomes treatment was reversed by TGF-β R1 inhibitor, SD208, in a dose-dependent manner." (PMID 23285052, 2012). "First, in the TRAMP model, we previously found that tumor development triggers enhanced TGF-β-dependent Smad2 and Smad3 phosphorylation in the tumor-draining lymph nodes compared to other tissues examined including the prostate." (PMID 22248703, 2011). "The p-Smad2 expression level was significantly higher in diffuse type carcinoma (p = 0.007), tumours with peritoneal metastasis (p = 0.017), and tumours with lymph node metastasis (p = 0.047)." (PMID 21110833, 2010). "In our head and neck patient series, Smad2 seems to be a TGFβ signaling node that enhances tumor aggressiveness." (PMID 20462450, 2010). "Loss on 18q included the well known 18q21.1 area which is known to harbour the tumour suppressor genes SMAD2 and SMAD4, which function in the TGFβ-pathway e.g. to mediate the growth-inhibitory effects of this cytokine." (PMID 17407575, 2007). "Among the 294 tumours for which gene dosage data (Smad2, Smad4 and DCC) were available, 167 tumours (57%) showed heterozygous loss of Smad4, and 73 out of 167 samples were randomly chosen for mutation analysis." (PMID 12569386, 2003). "Activation of TGF-β receptor type I (RI) and RII by TGF-β induces nuclear translocation of Smad proteins including Smad2 and Smad4 that have been originally identified as tumour suppressor genes." (PMID 10789724, 2000). "At least two different Smads, Smad2 and Smad4 (DPC4), have been implicated in human cancer and appear to have tumour-suppressor functions." (PMID 9862572, 1998). "The mechanism linking oncogenesis and the loss of chromosome 18 in these tumors has been investigated, with the hypothesis that the SMAD4 and SMAD2 tumor suppressors played an important role, but the answer is still unclear." (PMID 41416936, 2026).
tumor (continued). "Moreover, treatment with SIS3, a specific SMAD3 inhibitor, significantly improved CD107a expression in CD56dim tumor-infiltrating NK cells (TINKs)—a subset where we observed increased SMAD2–3 phosphorylation compared to their liver-resident counterparts." (PMID 41268557, 2025). "Furthermore, a significant increase in phosphorylation of the SMAD2–3 complex was observed in both total NK cells and the CD56dim subset within the tumor, relative to the liver." (PMID 41268557, 2025). "Furthermore, both immunohistochemistry (IHC) and Western blotting identified elevated SULF1 expression and increased phosphorylation of SMAD2/3 (TGFB pathway activation) in tumor and peritumoral tissues from transgenic Sulf1-Tg mice compared with WT." (PMID 41373732, 2025). "The TGF‐βpathway genes (THBS1 and SMAD2) report on epithelial–mesenchymal transition and immunosuppressive signaling, while Th2‐associated markers (CCR4, GATA3) indicate a helper T‐cell polarization state that favors tumor progression." (PMID 41407509, 2025). "TCS9725 inhibited TGF-β1-induced tumor migration and p-Smad2/3 activity in the RCC cells." (PMID 40699862, 2025). "In addition, we analysed SMAD2 and pSMAD2L in alveolar epithelial cells type 2 from tumour-free lung tissue as well as in benign and malignant T cells by Western blotting." (PMID 40319202, 2025). "Moreover, TGFBRi treatment further inhibited the phosphorylation of SMAD2/3 and tumor proliferation." (PMID 40335825, 2025). "Importantly, Western blot analysis of tumor extracts showed that Klk8 knockdown also significantly decreased the levels of pSmad2 relative to total Smad2." (PMID 40064965, 2025). "They found that SeNPs could inhibit PCa growth by reducing IKK-ɛ and SMAD2 mRNA levels in xenograft mice, suggesting that SeNPs could be used for anti-tumor purposes." (PMID 40388455, 2025). "Our analysis reveals that, regardless of the tumour stage, TGF-β exerts a potent suppressor effect on iCCA tumour cells that is dependent on a functional SMAD2/3/4 complex and that inhibition of TGF-β receptors boosts iCCA progression by promoting tumour cell growth." (PMID 40820091, 2025). "Among them, the TGFβ1/SMAD2/3 signaling pathway plays critical roles in tumor metastasis." (PMID 40291908, 2025). "Additionally, these tumor‐infiltrating γδ T cells exhibited reduced expression of STING and upregulated p‐Smad2 in tumor tissues as the tumor progressed." (PMID 39573933, 2025). "In contrast, the higher proportion of missense mutations in H/L patients, particularly within SMAD2 and CTNNB1, may result in more nuanced functional alterations that contribute to tumor progression through different biological mechanisms." (PMID 40869017, 2025). "Therefore, 8-Nitrotryp suppresses EMT in HCT116 and SW480 cells by inhibiting SMAD2 phosphorylation, thereby reducing tumor metastasis." (PMID 40918508, 2025). "To assess whether circulating 5a-HSA can reduce TGFβ activation in the tumor microenvironment, we analyzed the activation of intracellular TGFβ signaling mediators (SMAD2/3) in different models of tumor-bearing mice after systemic administration of 5a-HSA." (PMID 40055773, 2025). "In addition, high USP32 expression plays a crucial role in tumor growth, metastasis, immune infiltrates, and chemoresistance via the deubiquitination of various substrate proteins, such as Smad2, SHMT2, FDFT1, Rab7, SLC35F2, and BAG3." (PMID 40136417, 2025). "At the same time, many studies also support the tumor-promoting effects of SMAD2/3 in HCC." (PMID 38385079, 2024). "Moreover, TGF-β derived from TAMs inhibited T cell activity through phosphorylating Smad2/3 protein and inhibiting mitochondrial respiration, thus promoting the formation of tumor immunosuppressive microenvironment." (PMID 38970071, 2024).
tumor (continued). "However, the simultaneous knockdown of both Smad2 and Smad3 has a stronger effect on promoting in vivo tumor growth than the knockdown of Smad2 alone, suggesting that Smad3 plays a supporting role in the tumor suppressor function of Smad2." (PMID 38569937, 2024). "Emergent research illuminates that LIF, an immunomodulatory signaling molecule, might operate as a critical effector downstream of the TGF-β/Smad2/3 pathway, furnishing a pivotal axis in tumor immunoresponsivity and potentially metastasis." (PMID 38490994, 2024). "To further verify the role of the TGF-b1/Smad2/3 pathway in FBXO28 knockdown-mediated tumor inhibition, we performed rescue experiments in A2780 and SKOV3 cells with FBXO28 knockdown by transfecting a TGF-b1 overexpression plasmid to upregulate TGF-b1 expression." (PMID 38267923, 2024). "To evaluate whether SPON1 signaling through LRP8 can induce TGF-β1 activation, we evaluated several of our tumor models and spheroids for SMAD2 phosphorylation." (PMID 38716730, 2024). "In HM tumours only RGMB, SMAD2, AREG and RFX5 mutations correlated with low hypoxia." (PMID 39112715, 2024). "Genes for both Smad2 and Smad3 can be accepted as tumor suppressor genes." (PMID 38256080, 2024). "On the other hand, SMAD2/3 had tumor-suppressive effects in HCC." (PMID 38385079, 2024). "CCK-8, colony formation, and nude mice tumor transplantation assays showed that Smad2/3/4 complex could repress cell proliferation through TAT." (PMID 38769521, 2024). "SMAD2 was significantly overexpressed in tumor tissues compared with normal tissues in TCGA." (PMID 37790613, 2023). "Thus, we combined chemotherapeutic MMC with Smad2/3 inhibitor ITD-1 for target therapy in TRIM9-overexpressed tumor model." (PMID 37249822, 2023). "Moreover, exosomal circCOL1A1 promoted angiogenesis via inducing Smad2/3 signaling pathway in vitro, and it also accelerated tumor growth and angiogenesis in vivo." (PMID 37940881, 2023). "Furthermore, high PODNL1 expressions were positively related with the regulation of tumor-promoting TGF-β signaling through downregulating SMAD2/3:4 heterotrimer regulations transcription and up-regulating the pathway restricted SMAD protein phosphorylation." (PMID 37504302, 2023). "However, the onset of hyperplasia and tumor development was more rapid in the SMAD2/3-PR-cre mice than in the SMAD2/3-Ltf-cre model presented here." (PMID 36906706, 2023). "In vivo, LINC00707 expression was negatively correlated with Smad2 activation in tumor tissues." (PMID 37784093, 2023). "SMAD2 can promote the development of CRC by regulating the polarization of tumor macrophages." (PMID 36969909, 2023). "The tumour suppressor function of SMAD2/3 in the endometrium was found to be mediated by the PI3K/PTEN/AKT signalling pathway, which has an important role in regulating epithelial cell homeostasis and interfering with the effect of both pathways on endometrial carcinogenesis." (PMID 37685308, 2023). "SMAD1 was correlated with patient prognosis, and SMAD2 was correlated with tumor stage." (PMID 36969909, 2023). "In order to understand the stage of the tumor, the increase of SMAD2 value can be detected." (PMID 36969909, 2023). "Other pathways such as Smad2/3 and angiotensin signallings could also result in tumour angiogenesis, and strategies targeting these pathways have also been developed." (PMID 37403792, 2023). "Moreover, MIR155 is overexpressed in HL and targets SMAD2 as well, supporting the role of SMAD2 as a tumor suppressor in this malignancy." (PMID 37428779, 2023). "However, ovariectomized Smad2/3 cKO mice treated with E2 displayed expansion of the epithelial cells in the tumor mass." (PMID 36906706, 2023). "In addition, exosomal circCOL1A1 promoted angiogenesis via activating Smad2/3 pathway in vitro, and it also accelerated tumor growth and angiogenesis in vivo." (PMID 37940881, 2023).